MOG (myelin oligodendrocyte glycoprotein)
Diseases named in the same sentence as MOG in open-access papers (continued):
Sharing a sentence is not in itself a finding about the gene and the disease.
neuromyelitis optica spectrum disorder (continued). "Antineutrophil cytoplasmic antibodies (ANCA) testing for vasculitis was negative, as well as AQP4 and MOG antibodies for the workup of neuromyelitis optica (NMO)." (PMID 39650894, 2024). "Subsequent studies showed that MOG antibodies were also present in patients with optic neuritis, myelitis, neuromyelitis optica spectrum disorder (NMOSD) phenotype without aquaporin 4 (AQP4) antibodies, and brainstem and cerebral cortical encephalitis." (PMID 37789888, 2023). "We report on a patient with MFS that was positive for GQ1b and aquaporin-4 antibodies but negative for myelin oligodendrocyte glycoprotein antibodies and is devoid of any features of neuromyelitis optica spectrum disorder." (PMID 37581199, 2023). "Multiple sclerosis (MS), neuromyelitis optica spectrum disorder (NMOSD), acute disseminated encephalomyelitis (ADEM), myelin oligodendrocyte glycoprotein (MOG) encephalomyelitis, and idiopathic transverse myelitis (TM) represent the main diseases characterized by autoimmune demyelination." (PMID 35454978, 2022). "Discussion: an atypical optic neuritis may indicate a neuromyelitis optica spectrum disorder (NMOSD), which should be further characterized by determination of Aquaporin 4(AQP4)-IgG and MOG-IgG." (PMID 32705325, 2021). "HLA studies in neuromyelitis optica (SSP-PCR, sequence-specific primers–polymerase chain reaction; PCR-SSO, polymerase chain reaction–sequence specific oligoprobes; SBT, sequencing-based typing; MOG-Ab, myelin oligodendrocyte glycoprotein antibody)." (PMID 34675927, 2021). "Blood test for neuromyelitis optica-IgG antibody and myelin oligodendrocyte glycoprotein antibody were both negative." (PMID 33746872, 2021). "In the inflammatory neurological disease control group (INDC), as well as neuromyelitis optica spectrum disorders (NMOSD) group and patients diagnosed with MOG antibody-associated disease (MOGAD), no OMGP autoantibodies are detected." (PMID 33256847, 2020). "MOG-Abs are consistently identified in a range of acquired demyelinating syndromes (ADS) in adults and children with a clinical phenotype distinct of MS and AQP4-Ab neuromyelitis optica spectrum disorder." (PMID 30671648, 2019). "The presence of MOG-Ab identifies a subset of adults and children meeting the clinical and imaging criteria for neuromyelitis optica spectrum disorder (NMOSD) without antibodies to aquaporin-4." (PMID 30671648, 2019). "Anti-MOG antibodies were present in cases of neuromyelitis optica negative for anti-aquaporin-4 antibodies." (PMID 31544855, 2018). "Features suggestive of MOG-IgG as opposed to aquaporin-4 immunoglobulin G in neuromyelitis optica spectrum disorder." (PMID 29670575, 2018). "For example, we only performed serologic test for neuromyelitis optica without performing study on myelin oligodendrocyte glycoprotein." (PMID 29856811, 2018). "Antibodies to myelin oligodendrocyte glycoprotein (MOG-IgG) have been described in patients with neuromyelitis optica spectrum disorders (NMOSD) without aquaporin-4 antibodies (AQP4-IgG)." (PMID 28840314, 2017). "Antibodies against myelin oligodendrocyte glycoprotein (MOG-IgG) have been reported in patients with aquaporin-4 antibody (AQP4-IgG)-negative neuromyelitis optica spectrum disorders (NMOSD)." (PMID 27802824, 2016). "The effects of neuromyelitis optica MOG-IgG in the central nervous system have not been investigated in vivo." (PMID 24685353, 2014). "Other multicentre studies have shown higher accuracy for live versus fixed cell‐based assays in the detection of MOG antibodies, and a higher sensitivity for live CBA than tissue‐based immunofluorescence in the detection of aquaporin‐4 antibodies in patients with neuromyelitis optica." (PMID 39887819, 2025).
neuromyelitis optica spectrum disorder (continued). "Additional diagnostic evaluation included testing for myelin-oligodendrocyte glycoprotein (MOG) antibodies and anti-aquaporin 4 antibodies, to rule out other demyelinating conditions, specifically MOG antibody-associated disease (MOGAD) and Neuromyelitis Optica Spectrum Disorders (NMOSD)." (PMID 40269816, 2025). "As a result, MOG antibodies have been found in patients with optic neuritis, acute myelitis, neuromyelitis optica spectrum disorders (NMOSD) without aquaporin 4 (AQP4) antibodies, acute disseminated encephalomyelitis (ADEM), and brainstem and cerebral cortical encephalitis." (PMID 37545724, 2023). "The effect of smoking on the resolution of magnetic resonance imaging (MRI) lesions in patients with neuromyelitis optica spectrum disorders with aquaporin-4 positive antibody (NMOSD-AQP4) and myelin oligodendrocyte glycoprotein antibody-associated disease (MOGAD) has not been studied before." (PMID 37528605, 2023). "However, dimethyl fumarate for MOG antibody disease was not harmful compared with when disease-modifying drugs (DMDs) of MS were used for anti-aquaporin-4 antibody-positive neuromyelitis optica." (PMID 31824807, 2019). "Hence, some dual negative test results for AQP4-Ab and MOG-Ab may be false-negative since previous investigations revealed that AQP4-Ab can be detected positive in CSF samples of some AQP4-Ab-seronegative neuromyelitis optica patients." (PMID 38054007, 2023). "By targeting N-glycan branching in immune cells, GlcNAc may also be relevant to other inflammatory and demyelinating disorders, including neuromyelitis optica and myelin oligodendrocyte glycoprotein antibody disease, as well as non-neurological T cell and or B cell dependent autoimmune diseases." (PMID 37705084, 2023). "Extensive evaluation for multiple sclerosis (MS), neuromyelitis optica spectrum disorder (NMOSD), and myelin oligodendrocyte glycoprotein (MOG) antibody disease was consistently negative." (PMID 42211618, 2026). "At disease onset, MOG-IgG was positive by a fixed CBA, while AQP4-IgG and OCB of CSF were negative, thereby excluding neuromyelitis optica spectrum disorder and multiple sclerosis." (PMID 41459522, 2025). "Neuromyelitis optica spectrum disorders were excluded with negative anti-aquaporin-4 (NMO-IgG) and anti-myelin oligodendrocyte glycoprotein (MOG) antibodies." (PMID 40959376, 2025). "Oligoclonal bands, neuromyelitis optica (NMO)/aquaporin-4 (AQP4), and myelin oligodendrocyte glycoprotein (MOG) were negative." (PMID 39022493, 2024). "Our patient’s serum testing for neuromyelitis optica (NMO) and myelin oligodendrocyte (MOG) antibodies were negative, and suspicion for seronegative disease was lower on the differential." (PMID 39027742, 2024). "Despite rigorous confirmation with reliable assays, some individuals showing the neuromyelitis optica spectrum disorder (NMOSD) phenotype remain negative for both aquaporin-4 (AQP4) and myelin oligodendrocyte glycoprotein (MOG) antibodies." (PMID 35413922, 2022). "Serum Neuromyelitis Optica antibody (AQP4-IgG) and Myelin oligodendrocyte glycoprotein antibody (MOG-IgG) were negative." (PMID 35305566, 2022). "Serological testing for the anti-nuclear antibody, anti-phospholipid antibodies, neuromyelitis optica, anti-NMDA, AQP-4, and MOG antibodies was also negative." (PMID 33726699, 2021). "MOG-IgG was absent in 221 further controls, including 83 patients with AQP4-IgG-seropositive neuromyelitis optica spectrum disorders and 85 with multiple sclerosis (MS)." (PMID 27788675, 2016). "Neuromyelitis optica (NMO) and myelin oligodendrocyte glycoprotein (MOG) antibodies were negative." (PMID 39078559, 2024). "Currently, most researchers in the field believe that although MOG-ON is similar to AQP4-ON in clinical manifestations, unlike AQP4-ON, MOG-ON is not an immune subtype of neuromyelitis optica spectrum disorder (NMOSD), but a subtype of MOG antibody-related diseases (MOGAD)." (PMID 36969199, 2023).
neuromyelitis optica spectrum disorder (continued). "Finally, AIs are regularly negative also in AQP4-IgG-positive neuromyelitis optica spectrum disorders (NMOSD) and in MOG-IgG-positive encephalomyelitis, two diseases in which a direct pathogenic impact of the antibody has been proven or is﻿ highly likely." (PMID 27776522, 2016).
experimental autoimmune encephalomyelitis (364 papers, 2005 to 2026). An autoimmune demyelinating disease of the central nervous system that is produced experimentally in animals by the injection of homogenized brain or spinal cord in Freund's adjuvant. "Pathogenic mechanisms and therapeutic implications from experimental autoimmune encephalomyelitis models in MOG-associated autoimmune disease." (PMID 40463369, 2025). "MS can be modeled in mice by vaccination against myelin oligodendrocyte glycoprotein (MOG), resulting in the establishment experimental autoimmune encephalomyelitis (EAE), the development of which depends on pathogenic autoreactive Th1 and Th17 cells." (PMID 38777879, 2024). "PDCD4-deficient mice, immunized with myelin oligodendrocyte glycoprotein to induce experimental autoimmune encephalomyelitis, have shown resistance to autoimmune encephalomyelitis and developed a reduced degree of spinal cord inflammation." (PMID 36833311, 2023). "The development of myelin oligodendrocyte glycoprotein (MOG)-induced experimental autoimmune encephalomyelitis was enhanced in C1qtnf3–/– mice associated with increase of Th17 cell population." (PMID 34925309, 2021). "Anti-MOG antibodies (MOG-IgG) can cause demyelination in vitro and persuade experimental autoimmune encephalomyelitis." (PMID 32825639, 2020). "Mice without Ncf1 display augmented disease severity in two models of autoimmune disorders, experimental autoimmune encephalomyelitis (EAE) provoked by native myelin oligodendrocyte glycoprotein (MOG) and arthritis caused by collagen or serum." (PMID 32380695, 2020). "In a transgenic mouse model with endogenous MOG-recognizing T cells, constitutive production of autoantibody against MOG caused experimental autoimmune encephalomyelitis." (PMID 30382857, 2018). "It was shown in several studies that PKC-θ-deficient mice were resistant to experimental autoimmune encephalomyelitis after injection of myelin oligodendrocyte glycoprotein (MOG)." (PMID 26528291, 2015). "Here, we demonstrated that DCIR deficiency induced spontaneous development of experimental autoimmune encephalomyelitis (EAE)-like encephalomyelitis in 2D2 TCR transgenic mice (2D2Tg) expressing a myelin oligodendrocyte glycoprotein (MOG)-specific T cell receptor." (PMID 42256301, 2026). "In this study, we generated murine tolDC presenting myelin oligodendrocyte glycoprotein (MOG) using mRNA electroporation and we assessed the efficacy of MOG mRNA-electroporated tolDC to dampen pathogenic T cell responses in experimental autoimmune encephalomyelitis (EAE)." (PMID 31416452, 2019). "Of note, NRF2‐deficient mice also develop a more severe myelin oligodendrocyte glycoprotein (MOG)‐induced experimental autoimmune encephalomyelitis with increased oxidative damage in the CNS, finally leading to enhanced demyelination and more pronounced axonal loss." (PMID 29997171, 2018). "Furthermore, MOG is a well-established autoantigen widely used to evoke the animal model of MS, namely experimental autoimmune encephalomyelitis (EAE), with infiltrating monocytes being the major cause of pathogenesis." (PMID 28828577, 2017). "CARMA1- or MALT1-deficient mice are fully protected from induction of experimental autoimmune encephalomyelitis (EAE) by immunization with myelin oligodendrocyte glycoprotein (MOG), and treatment of mice with the MALT1 inhibitor mepazine attenuates onset and progression of the disease." (PMID 26507244, 2016). "The APLEC gene cluster has also been implicated in other disease models, including MOG (myelin oligodendrocyte glycoprotein)-induced experimental autoimmune encephalomyelitis (EAE), where it plays a putative role in disease susceptibility and severity, and antibody response." (PMID 27736747, 2016).
experimental autoimmune encephalomyelitis (continued). "It had been implicated that CXCR3 is highly expressed on pro-inflammatory human CD4+Th17 cells, “pathogenic” human Th1/17 cells, and myelin oligodendrocyte glycoprotein-specific CD4+ T cells in experimental autoimmune encephalomyelitis mice in combination with other biomarkers." (PMID 26150899, 2015). "The HLA-II-Tg mice studies showing that HLA-DRB1*1501-Tg mice are susceptible to myelin basic protein (MBP)- or myelin oligodendrocyte glycoprotein (MOG)-induced experimental autoimmune encephalomyelitis (EAE) are also consistent with the primary contribution of DRB1*1501 to MS pathogenesis." (PMID 25360418, 2014). "In the myelin oligodendrocyte glycoprotein (MOG) peptide-induced murine experimental autoimmune encephalomyelitis (EAE) model, the exosomes of membrane-associated TGF-ß1 gene-modified dendritic cells (mTGF-ß1-EXO) were found to prevent both the development and the progression of the disease." (PMID 26082318, 2013). "In the present study, we aimed to evaluate the precise mechanisms by which a DNA vaccine encoding the myelin oligodendrocyte glycoprotein (MOG) induces immune regulation and efficiently suppresses experimental autoimmune encephalomyelitis (EAE) in both prophylactic and therapeutic settings." (PMID 22727044, 2012). "Furthermore, adult Ptprz-deficient mice were less susceptible to experimental autoimmune encephalomyelitis (EAE) induced by active immunization with myelin/oligodendrocyte glycoprotein (MOG) peptide than were wild-type mice." (PMID 23144976, 2012). "Indeed, inhibitory signals mediated by HVEM have been postulated to explain observations in HVEM-/- mice of increased mortality during ConA-mediated autoimmune hepatitis, and increased susceptibility to MOG peptide-induced experimental autoimmune encephalomyelitis (EAE)." (PMID 21533159, 2011). "MOG-specific T cells are required to initiate CNS inflammation in experimental autoimmune encephalomyelitis (EAE), a key model for autoimmune neuroinflammation." (PMID 40717732, 2025). "In the MOG-induced experimental autoimmune encephalomyelitis (EAE) model of MS, a single prophylactic injection of TPC-MOG35-55 prior to disease induction significantly attenuated disease severity, whereas TP-treated mice developed clinical symptoms." (PMID 40165970, 2025). "In multiple sclerosis (MS), rAAV vectors encoding myelin oligodendrocyte glycoprotein (MOG) induce antigen-specific Foxp3+ T-cell expansion in the liver, bypassing MHC restrictions to alleviate experimental autoimmune encephalomyelitis (EAE), a key MS mode." (PMID 40284659, 2025). "We then characterized the pharmacological properties of the optimized LPX3 formulation in vitro and in vivo before assessing its efficacy in a MOG-induced experimental autoimmune encephalomyelitis (EAE) mouse model of MS." (PMID 40564995, 2025). "ARAP deficiencies analyzed in vivo presented a less severe clinical course of experimental autoimmune encephalomyelitis (EAE) following immunization of mice with the myelin oligodendrocyte glycoprotein (MOG)." (PMID 40264755, 2025). "In a MOG-induced experimental autoimmune encephalomyelitis (EAE) mouse model of MS, both prophylactic and therapeutic oral administration of LPX3 significantly delayed disease onset, reduced symptom severity, and improved survival." (PMID 40564995, 2025). "Engineered the MOG/NF-M cross-reactive TCR-Tregs displayed enhanced immunoregulatory activity compared to the MOG-specific TCR-Tregs in a murine model of experimental autoimmune encephalomyelitis (EAE) induced by MOG." (PMID 41373714, 2025). "In the 1980s, MOG was identified as a target in experimental autoimmune encephalomyelitis, however, early ELISA assays showed that MOG antibodies were widely present in both healthy individuals and multiple sclerosis patients, lacking specificity." (PMID 40406135, 2025).
experimental autoimmune encephalomyelitis (continued). "To examine the role of ATXN1 in EAE, we immunized 8-week-old WT, f-ATXN1146Q/2Q, and Atxn12Q/− female mice, with myelin oligodendrocyte glycoprotein (MOG) peptide 35 to 55 (MOG35–55) to induce experimental autoimmune encephalomyelitis (EAE)." (PMID 40321775, 2025). "In the mice initiated with myelin oligodendrocyte glycoprotein (MOG)-induced experimental autoimmune encephalomyelitis (EAE), TRBV13-2 is preferentially used in the TCRβ gene of MOG-specific T cells." (PMID 41516289, 2025). "These mice also exhibit resistance to experimental autoimmune encephalomyelitis (EAE) attributed to defective generation of myelin oligodendrocyte glycoprotein (MOG)-specific T cells." (PMID 40362578, 2025). "CQ attenuated demyelination, microglial activation, and enhanced autophagy in myelin oligodendrocyte glycoprotein (MOG)-induced experimental autoimmune encephalomyelitis (EAE), one of the most commonly used animal models of MS." (PMID 38037913, 2024). "An in vivo experiment using the experimental autoimmune encephalomyelitis (EAE) MS model was conducted using Myelin oligodendrocyte glycoprotein (MOG) as the activating peptide." (PMID 38778343, 2024). "In our study, panobinostat was found to alleviate the progression of MOG-triggered experimental autoimmune encephalomyelitis within C57BL/6 mice." (PMID 39596104, 2024). "We investigated the effect of a galactose-rich diet during neuroinflammation using myelin oligodendrocyte glycoprotein-induced experimental autoimmune encephalomyelitis (MOG-EAE) as a model disease." (PMID 39185426, 2024). "According to a recent animal study on MOG-IgG experimental autoimmune encephalomyelitis (EAE), inflammation was found to initiate primarily in the white matter region during both acute and chronic stages of the disease." (PMID 39318613, 2024). "Using an animal model of MS, Allan and Yates demonstrated that cathepsin L−/− attenuates myelin oligodendrocyte glycoprotein (MOG) antigen presentation and the development of experimental autoimmune encephalomyelitis (EAE)." (PMID 37958596, 2023). "PubMed was searched for the terms “MOGAD,” “optic neuritis,” “MOG antibodies,” and “experimental autoimmune encephalomyelitis” alone or in combination, to find articles of interest for this review." (PMID 36729854, 2023). "Isolated spleens from oligodendrocyte glycoprotein (MOG) induced experimental autoimmune encephalomyelitis (EAE) mice." (PMID 37242947, 2023). "Previously, it was identified that VA was sensitive to identify the onset of acute optic neuritis in myelin oligodendrocyte glycoprotein (MOG)-induced experimental autoimmune encephalomyelitis (EAE) mice." (PMID 38152638, 2023). "It has been shown that amitriptyline modulates depressive-like behavior in a myelin oligodendrocyte glycoprotein experimental autoimmune encephalomyelitis (MOG-EAE) model of MS in mice." (PMID 36979303, 2023). "Commonly used models include myelin oligodendrocyte glycoprotein (MOG)-induced experimental autoimmune encephalomyelitis (EAE) and toxin and/or virus-induced demyelination models, such as cuprizone (CPZ) and lysophospholipid, among others." (PMID 37841264, 2023). "First, the clinical presentations observed in anti-MOG autoantibody-positive patients resemble those seen in experimental autoimmune encephalomyelitis (EAE) induced by MOG immunization." (PMID 36816137, 2023). "Relative to wild-type mice, hypomorphic mice with a reduction in TMEM106B have increased axonal damage and lipid droplet accumulation in the spinal cord following myelin-oligodendrocyte-glycoprotein-induced experimental autoimmune encephalomyelitis." (PMID 37443768, 2023). "Myelin oligodendrocyte glycoprotein (MOG)-induced experimental autoimmune encephalomyelitis (EAE) is a rodent model of MS, which predominately manifests in the spinal cord (SC)." (PMID 37957728, 2023).